PPIEL (peptidylprolyl isomerase E like (pseudogene))
Synonyms: PPIEP1
Gene: Transcribed unprocessed pseudogene on chromosome 1 (39,531,838 to 39,558,707, reverse strand). Ensembl gene ENSG00000243970.
Diseases named in the same sentence as PPIEL in open-access papers:
PPIEL is named in the same sentence as 1 disease in open-access papers, as found by Europe PMC text mining. Sharing a sentence is not in itself a finding about the gene and the disease. The quoted sentences say what the papers report.
colon cancer (1 paper, 2017). "For example, the imprinted PPIEL locus is located ~373 kb from the MYCL1 oncogene and co-amplification of both regions was observed in 98% of lung, 91% in liver, 97% in breast and 100% in colon cancer cell lines harboring copy-number gains of 1p34." (PMID 28883545, 2017).